APOE (apolipoprotein E)
Diseases named in the same sentence as APOE in open-access papers (continued):
Sharing a sentence is not in itself a finding about the gene and the disease.
preeclampsia (16 papers, 2008 to 2026). Preeclampsia is a hypertensive disorder of pregnancy that is characterized by new-onset hypertension with proteinuria presenting after 20 weeks of gestation, and depending on mild or severe forms may initially present with severe headache, visual disturbances, and hyperreflexia. "The presence of the HDL APOE-e4 allele in preeclamptic mothers was associated with an approximately eightfold higher risk of preeclampsia (adjusted OR = 8.4; 95% CI: 2.51 to 28.17; p = 0.001)." (PMID 35658865, 2022). "Circulating cholesterol has been widely described as a risk factor for preeclampsia, and some APOE alleles have been associated with PE." (PMID 22029530, 2011). "It has been postulated that ApoE levels and polymorphisms of its gene are associated with an increased risk of preeclampsia." (PMID 18790389, 2008). "In addition, higher concentrations of triacylglycerides and LDL and lower HDL concentrations were found in pregnant women with severe preeclampsia whose newborns were carriers of the APOE-e4 allele." (PMID 35658865, 2022). "Moreover, pregnancy outcomes, inflammatory and apoptosis biomarkers were evaluated to determine the potential effects of apoE and iNOS, as well as alteration of iNOS activity secondary to apoE deficiency in preeclampsia." (PMID 23472151, 2013). "And apoE polymorphism in women may be a risk factor for preeclampsia." (PMID 23472151, 2013). "Thus, the dyslipismia of apoE−/− may present as a pathogenic cause in inflammatory response and apoptosis of preeclampsia." (PMID 23472151, 2013). "Certain protective mechanisms in late preeclampsia have also been demonstrated using untargeted proteomics: apolipoprotein E (APOE), apolipoprotein C4 and C2 (APOC4-APOC2) were all significantly increased in LOP, whereas they were marginally increased in EOP." (PMID 37740793, 2024). "In a subsequent study, the authors observed that the glycosylation pattern of ApoE in women with preeclampsia differs from that in healthy pregnant women." (PMID 34281251, 2021). "For example, an increase in concentration of the deglycosylated ApoE isoform and a decrease in the level of glycosylated ApoE isoform, in combination with other proteins, can be used as a factor distinguishing healthy pregnancy from preeclampsia." (PMID 34281251, 2021). "In preeclampsia plasma, they found an increase in concentration of the deglycosylated ApoE isoform and a decreased level of glycosylated ApoE isoform." (PMID 34281251, 2021). "Seven alleles were significantly or marginally significantly associated with preeclampsia, which involved six genes (rs4762 in AGT, rs1800896 in IL-10, rs1800629 and rs1799724 in TNFα, rs2070744 in NOS3, rs7412 in APOE, and rs2549782 in ERAP2)." (PMID 30112393, 2018). "Elevated lipid metabolism and inflammatory/apoptosis parameters suggest a potentially significant role of apoE in preeclampsia pathology, as well as a relationship between iNOS and preeclampsia progression." (PMID 23472151, 2013). "In this study we established murine apoE and iNOS KO models and investigated their potential roles in apoptosis and inflammatory process of preeclampsia pathology using Western blot." (PMID 23472151, 2013). "Though we did not primarily aim to analyze the association between ApoE genotype and the incidence of preeclampsia and the HELLP syndrome, our study does partly allow us to draw certain conclusions." (PMID 28480219, 2017). "Assuming that each woman has a baseline risk for AD influenced by APOE genotype and history of having children, it is not known if having a pregnancy complicated by preeclampsia or preterm labor further accelerates the underlying pathophysiologic processes leading to AD." (PMID 38982272, 2024). "Our study suggested that apoE and iNOS may offer placental protection in women with preeclampsia." (PMID 23472151, 2013).
preeclampsia (continued). "In addition, potential apoptosis in apoE−/− mice provided evidence that the deficit of apoE may lead to placental apoptosis contributing to preeclampsia, supporting previous works by Reckless and Chen in the liver of apoE−/− mice." (PMID 23472151, 2013). "In preeclampsia plasma, there were no changes in total ApoE plasma concentration; however, the level of a deglycosylated form of ApoE was increased, concomitant with the decreased level of a highly sialylated glycoform of ApoE." (PMID 39169951, 2024). "The diverging conclusions of their study are probably caused by the small sample-size (n = 141 with 47 patients suffering on preeclampsia) with ApoE e4 not being normally distributed in their control group." (PMID 28480219, 2017).
prion disease (16 papers, 2011 to 2026). A transmissible disease that is caused by a protein that is able to induce abnormal folding of normal cellular proteins, leading to characteristic spongiform brain changes, which are associated with neuronal loss without an inflammatory response. "To further assess the role of APOE genotype in prion disease, we performed association analyses based on various histological, biochemical and genetic variables known to affect the CJD pathogenesis and phenotype." (PMID 30961668, 2019). "Apolipoprotein E and major prion protein, typically associated with Alzheimer's and prion's disease respectively, were detected only in the aggregates of KO cells." (PMID 25047918, 2014). "The latency period of prion disease was determined through serial locomotor testing, and the differences across animals of different APOE genotypes were compared using the Kaplan-Meier estimator." (PMID 41282061, 2025). "This is consistent with reports from human prion disease where ApoE was also reported to be up-regulated." (PMID 36378750, 2022). "Apolipoprotein E co-localisation was found to occur in moderately mature lesions in prion diseases, where it contributes to the aggregation of PrPsc after changes from cellular PrP isoform to PrPsc." (PMID 34208880, 2021). "Despite similarities between AD and prionoses the effect of APOE genotype in prion diseases has been only minimally explored." (PMID 34565486, 2021). "In this study we examined changes in the apoE expression in a murine model of prion disease and the effects of apoE absence on prion pathomechanisms." (PMID 34565486, 2021). "ApoE is localised within PrPTSE deposits, which supports the theory that it actively contributes to the pathogenesis of amyloid formation in prion diseases." (PMID 34208880, 2021). "It is well-established that the APOE ε4 allele and homozygosity at polymorphic codon 129 in the PRNP gene are the major genetic risk factors for AD and human prion diseases, respectively." (PMID 21799773, 2011). "Our findings further suggests that upregulation of astrocytic apoE expression and or its lipidation can be of therapeutic benefit in prion disease through enhancing phagocytic characteristics of activated microglia and promoting clearance of neuronal debris and PrPSc." (PMID 34565486, 2021). "Furthermore, proteomic studies pointed to APOE as a potential biomarker for prion disease by showing significantly elevated levels of the protein in prion-infected mice and its co-localization with PrPSc deposits in vivo." (PMID 30961668, 2019). "The APOE ε4 allele is a major risk factor for AD; whereas homozygosity at polymorphic codon 129 (Met to Val) in the PRNP gene is a well-established susceptibility marker for human prion diseases." (PMID 21799773, 2011). "Our findings indicate that the apoE protein directly interacts with PrP but only in prion disease and not under physiological conditions." (PMID 41282061, 2025). "Furthermore, deletion of Trem2 or ApoE in mice does not affect prion pathogenesis or PrPSc accumulation, suggesting that TREM2-APOE microglia signaling described in other neurodegenerative disease models does not influence prion disease." (PMID 32381108, 2020). "Interestingly, prion disease specifically targets ABCA1, but affects cholesterol efflux not only to the lipid-free apoA-I, which is the preferred substrate of ABCA1, but also to HDL and lipidated apoE, which are preferred substrates for two other transporters, ABCG1 and SR-BI." (PMID 24280226, 2014).
subarachnoid hemorrhage (16 papers, 2007 to 2025). A serious neurological disorder characterized by intracranial hemorrhage into the subarachnoid space. "Among its hemorrhagic manifestations, cortical superficial siderosis (cSS) and convexity subarachnoid hemorrhage (cSAH) are gaining increasing attention, particularly in individuals carrying the apolipoprotein E (APOE) ε2 allele." (PMID 40589441, 2025). "For example in adults, neuroglobin gene haplotype has a strong influence on outcome after TBI, bcl-2 gene single nucleotide polymorphisms also influence outcome after TBI, and apoE genotype predicts outcome following subarachnoid hemorrhage." (PMID 31275228, 2019). "Subarachnoid haemorrhage or APOE ɛ4 possession in isolation (medium risk) predicted 44–64% probability of moderate or severe CAA." (PMID 29331631, 2018). "During the last few decades, several studies have demonstrated that ApoE is associated with an increased risk of subarachnoid hemorrhage, hypertensive cerebral hemorrhage, amyloid angiopathy and angiorrhexis." (PMID 30031394, 2018). "Apolipoprotein E (Apoe) genetic polymorphisms have been implicated in the long term outcome of subarachnoid haemorrhage (SAH), but little is known about the effect of Apoe on the early brain injury (EBI) after SAH." (PMID 27463015, 2016). "The multivariable prediction model for CAA-associated lobar intracerebral haemorrhage included three predictors: APOE ɛ4 possession, subarachnoid haemorrhage, and finger-like projections." (PMID 29331631, 2018). "For the rule-in criteria, subarachnoid haemorrhage and either APOE ɛ4 possession or finger-like projections had 96% specificity (95% CI 78–100)." (PMID 29331631, 2018). "The presence of subarachnoid haemorrhage and APOE ɛ4 possession or finger-like projections was 96% specific with a positive likelihood ratio 16·6." (PMID 29331631, 2018). "We tested for association of variants in APOE and ELN with subarachnoid hemorrhage (SAH) in a population-based study." (PMID 17672902, 2007). "Subarachnoid haemorrhage or APOE ɛ4 possession separated low from medium or high probability groups, and had a sensitivity of 100% (95% CI 88–100) meaning that the absence of these two predictors with lobar intracerebral haemorrhage ruled out moderate or severe CAA." (PMID 29331631, 2018). "There have also been reports in recent years that ApoE may play a role in some hemorrhagic diseases, such as hypertensive cerebral hemorrhage and subarachnoid hemorrhage." (PMID 30031394, 2018). "Neither subarachnoid haemorrhage nor APOE ɛ4 possession was 100% sensitive for moderate or severe CAA with a negative likelihood ratio of 0; a negative likelihood of less than 0·1 means a negative test is good at ruling out a diagnosis." (PMID 29331631, 2018). "For the rule-out criteria, neither subarachnoid haemorrhage nor APOE ɛ4 possession had 100% sensitivity (95% CI 88–100)." (PMID 29331631, 2018).
all (15 papers, 2021 to 2026). "Although there are numerous studies examining the lipid profile of children treated for ALL, this research about the association between LpL and APOE gene polymorphisms and lipid levels in these patients is unique." (PMID 38507115, 2024). "The present study aimed to evaluate potential associations between LpL and APOE genotype or alleles with lipid profile alterations during treatment and also with ALL risk subgroup." (PMID 38507115, 2024). "Lipid abnormalities in children being treated for ALL may be associated with the APOE genotype, which is also possibly associated with risk stratification." (PMID 38507115, 2024). "In conclusion, it seems that lipid abnormalities during treatment in children with ALL could be associated with the ApoE genotype which is also possibly associated with risk stratification." (PMID 38507115, 2024). "The association between the genetic background of LpL and apoE and the lipid profile of children with ALL treated with l-asparaginase has not been previously studied." (PMID 38507115, 2024). "The present study showed that the lipid profile of children with ALL was not affected by any of the studied polymorphisms except rs429358 of the APOE gene." (PMID 38507115, 2024). "However, the association of the genetic background of LpL and apoE with the lipid profile in children with ALL receiving asparaginase has not been previously studied." (PMID 38507115, 2024).
Cerebral ischemia (15 papers, 2012 to 2025). Restriction of arterial blood supply to the brain associated with insufficient oxygenation to support the metabolic requirements of the tissue. "Additionally, another aspartyl peptidase, CatE, processes lipid‐free recombinant human apoE to a much greater extent than lipidated apoE and appears to be involved in neurodegeneration associated with brain ischemia and aging." (PMID 35067006, 2022). "Studies have also found that the up-regulation of P-gp after cerebral ischemia is related to apolipoprotein E, liver X receptor, and inflammatory mediators." (PMID 38221931, 2024). "Since ApoE is a known regulator of lipid homeostasis, we studied the impact of a high-cholesterol diet in aged mice in the context of relevant human ApoE isoforms on the outcome of focal brain ischemia." (PMID 23957944, 2013). "In earlier studies also the neuroprotective effect of fenofibrate could be seen in apoE null mice only after 14 days of treatment prior to onset of cerebral ischemia." (PMID 22514742, 2012). "Six valuable factors (smoking, orthostatic hypotension, preoperative MRI with silent brain ischemia or infarction, MAOBIs, HAMA score, and APOE level in plasma) were selected to establish the predictive model." (PMID 36483978, 2022).
emphysema (15 papers, 2010 to 2023). "The findings of the present study are partially substantiated by a study reporting that ApoE−/− mice on a WD for 10 weeks developed inflammation and emphysema." (PMID 25975841, 2015). "Previous studies showed that APOE mutant mice could be a good chronic obstructive pulmonary disease model exhibiting emphysema, pulmonary inflammation and airway obstruction." (PMID 35407693, 2022). "To determine the molecular mechanisms underlying CS-induced lung emphysema, we applied RCR to transcriptomic data sets derived from lungs of five mouse genotypes (C57BL/6, ApoE−/−, A/J, Nrf2−/− and CD1), susceptible to emphysema development following a prolonged (5–6 months) exposure to CS." (PMID 25962837, 2015). "Interestingly, our preliminary data showed that overexpression of SIRT1 in ApoE-/- mice in double transgenic mice protected, whereas knockdown of SIRT1 in ApoE-/- mice aggravated the lung phenotype (inflammation and emphysema)." (PMID 20663150, 2010). "It is possible that CS augments the generation of lipid peroxidation derived 4-HNE which would activate inflammatory signaling pathways in the lungs of ApoE-/- mice, thereby leading to an increased inflammatory response and development of premature emphysema in these mice." (PMID 20663150, 2010). "These HYPs were conserved across five susceptible mouse models (C57BL/6, ApoE−/−, A/J, CD1, and Nrf2−/−), suggesting that a core set of biological features may be closely related to emphysema development in a mouse model and may potentially be translatable to human disease." (PMID 25962837, 2015). "However, it is not known whether T and B cells are involved in the inflammatory response seen in ApoE-/- mice, since these cells also play an important role in the development of emphysema/COPD in humans." (PMID 20663150, 2010). "We measured the airspace enlargement and decline in lung function, which are the characteristics of pulmonary emphysema/COPD, in WT and ApoE-/- mice exposed to air or CS." (PMID 20663150, 2010). "Apolipoprotein E is the DAP that has most interactions with other DAPs, which indicates it may serve as a key molecule in the mechanism of emphysema." (PMID 34277700, 2021). "Furthermore, in the ApoE−/− mouse model, which is commonly used to study atherosclerosis and emphysema, exposure to THS 2.2 aerosol did not induce a change in the lipid profile or enlargements of aortic plaque area, nor lung inflammation or emphysema, unlike cigarette smoke." (PMID 30143474, 2018).
hepatitis C (15 papers, 2010 to 2024). "ApoE-Є4 shows less severe liver damage during hepatitis C infections, the allele frequency remained high in populations where food was scarce until recently, and the allele is associated with higher circulating cholesterol levels." (PMID 39286457, 2024). "Though of interest, as APOE alleles are suggested to affect fibrosis progression in hepatitis C infection, a much larger patient population would be needed to ensure adequate power for subtle genotype effects." (PMID 25051269, 2014). "Several studies have shown the APOE genotype to influence infection susceptibility and damage in certain diseases caused by viruses, including human immunodeficiency virus and hepatitis C and B, protozoa and fungi." (PMID 25051269, 2014). "The impact of APOE alleles on hepatitis C infection are likely viral strain- and cell-specific." (PMID 33800954, 2021). "APOE ɛ4 has been suggested to be protective against hepatitis C infection as well as carriers being observed to have a better prognosis post infection." (PMID 34721516, 2021). "Given the primary role of apoE in the HCV life cycle, several studies investigated the possibility of a correlation between apoE isoform and hepatitis C infection." (PMID 23698400, 2013). "In man, APOE is also involved in hepatitis C, HIV-1, and herpes simplex infectivity, and APOE4 facilitates the binding of C. pneumoniae elementary bodies to host cells." (PMID 22254144, 2011). "In this study, we further determined the physiological importance of apoE and HSPGs in HCV attachment using clinical HCV of genotype 1b derived from hepatitis C patients and human embryonic stem cell-differentiated hepatocyte-like cells (DHHs)." (PMID 23844141, 2013). "To further corroborate the physiological importance of apoE in the mediation of HCV attachment, we carried out HCV binding studies using a clinical HCV of genotype 1b obtained from hepatitis C patients together with human embryonic stem cell-differentiated hepatocyte-like cells (DHHs)." (PMID 23844141, 2013). "In the present study, we further determined the physiological importance of apoE and HSPGs in the HCV attachment using a clinical HCV of genotype 1b (HCV1b) obtained from hepatitis C patients and human embryonic stem cell-differentiated hepatocyte-like cells (DHHs)." (PMID 23844141, 2013). "To examine whether C1q-ApoE complexes form in human livers with acute and chronic inflammatory diseases, we examined human liver biopsies obtained from patients who were diagnosed with NAFLD or hepatitis C and hepatitis B/C coinfection." (PMID 36304458, 2022). "The physiological importance of apoE, HSPGs, and their interactions in vivo are further supported by several lines of evidence obtained from the present study with HCV of genotype 1b derived from hepatitis C patients in conjunction with DHHs which resemble primary human hepatocytes." (PMID 23844141, 2013).